NOVA1 (NOVA alternative splicing regulator 1)
Diseases named in the same sentence as NOVA1 in open-access papers (continued):
Sharing a sentence is not in itself a finding about the gene and the disease.
neuroblastoma (1 paper, 2015). Neuroblastoma (NB) is the most common solid, extracranial childhood tumor. "Notably, TTP knockdown was sufficient for HuB/C/D and Nova1 upregulation in Neuro2a neuroblastoma cells." (PMID 26144867, 2015).
cancer (25 papers, 2014 to 2024). A tumor composed of atypical neoplastic, often pleomorphic cells that invade other tissues. "Dysregulated NOVA1-mediated splicing is linked to various cancers, including colorectal, pancreatic, lung, and prostate." (PMID 37924098, 2023). "Nova1 is directly targeted by miR-181-5p and miR-203a-3p in neurons, and is also expressed in various other tissues and is often implicated in cancers." (PMID 34769047, 2021). "High intratumoral Nova1 is associated with poor survival rate and increased cancer recurrence rate." (PMID 24608171, 2014). "Among these 17 “RNA-binding” genes, RBFOX2 and NOVA1 have been reported to be essential for maintaining cancer stemness and are known for their roles in the EMT." (PMID 39420119, 2024). "The connection with RNA processing factors, like TNRC6B and NOVA1, further underscores the multifaceted nature of miRNA-mediated regulatory networks in the context of cancer recurrence." (PMID 39070144, 2024). "MiR-27a-3p upregulation has been identified in a variety of human cancers, and miR-27a-3p modulates cancer progression by targeting multiple targets including NOVA1, FBXW7 and BTG2." (PMID 35348441, 2022). "The results of Cell Counting Kit-8 and colony formation assays revealed that down-regulation of Nova1 produced a remarkable inhibition in the proliferation rate of cancer cells." (PMID 36284263, 2022). "NOVA1 is considered to be a brain-specific splicing factor that plays an important role in the nervous system and cancer." (PMID 33799408, 2021). "Focusing on β-deletion splicing regulation, we found the NOVA1 trans-acting factor to mediate alternative splicing in a cancer-dependent manner." (PMID 33924498, 2021). "Neuro-oncological ventral antigen 1 (Nova1) is a neuron-specific RNA-binding protein that functions as an oncogene involved in the aberrant immune response, the resistance of cancer cells to hypoxia-related apoptosis induction, and tumor progression." (PMID 34425750, 2021). "The roles of NOVA1 in cancer are not yet fully understood, but correlations between Nova1-targeting miRNAs and NOVA1 expression have been described in multiple types of cancers." (PMID 34769047, 2021). "NOVA1 is known to be involved in the downregulation of E6 and E7 proteins in HPV associated cancers and is hence indicated as a good prognosticator in HPV+ patients." (PMID 31310629, 2019). "Although Nova1 was an unfavorable predictor for cancer recurrence, the relationship between Nova1 expression and early recurrence (defined as cancer relapses within 24 months) was further analyzed." (PMID 24608171, 2014). "Unfortunately, to date, there are few case reports and little discussion in the literature addressing the Nova1 autoantibodies expressed in malignant tumors." (PMID 24608171, 2014). "Next an inducible expression system manipulated by Dox, either knockdown of Nova1 in Huh7 cell or overexpression of Nova1 in SMMC-7721 cell, was established to study the role of Nova1 in cancer cell behavior." (PMID 24608171, 2014). "Further investigation into AGO1, TNRC6B, NOVA1, MMP16, and their connection to miRNA processing could provide deeper insights into the molecular mechanisms underlying cancer recurrence." (PMID 39070144, 2024). "Recently, NOVA1 had been reported to serve as downstream target gene for a series of microRNAs and was demonstrated to be responsible for the regulation of cellular biological behavior in cancer." (PMID 36284263, 2022). "In recent years, the roles of NOVA1 in neuronal cells and cancer have been revealed." (PMID 33799408, 2021). "NOVA1 downregulation also significantly decreases cancer cell growth both in vitro and in vivo." (PMID 31186051, 2019). "Further, NOVA1 may be a regulator of growth and invasion-related signaling in cancer cells, coupling telomere length maintenance to other cancer cell characteristics." (PMID 30082712, 2018).
cancer (continued). "NOVA1 (neuro-oncological ventral antigen 1) is known to be involved in the neuronal splicing program; the role of NOVA1 has been rarely investigated in other types of cells or cancers." (PMID 26673617, 2016). "Further, autoantibodies against Nova1 were found in the serum and/or cerebrospinal fluid of patients before the cancer becomes symptomatic, which implies that these antibodies may have utility for early detection of these disorders." (PMID 24608171, 2014). "Interestingly, targeting NOVA1 can also downregulate the hTERT transcription, a possible reason is that NOVA1 may regulate the upstream transcription factors of hTERT in cancer cells." (PMID 31186051, 2019). "Other splicing regulatory factors, such as RNA-binding motif protein 4 (RBM4), whose expression is suppressed in cancer, is a tumor suppressor that dysregulates exon 4 skipping of NOVA alternative splicing regulator 1 (NOVA1) and intron 11 retention of PTB." (PMID 34330892, 2021). "By employing hTERT as a model gene, we show the coordination of the splicing factors NOVA1 and PTBP1 in cancer by regulating telomerase that is expressed in the vast majority of cancer cell types." (PMID 30568224, 2019). "For instance, NOVA1, NRXN1, TMEM132C, USP44, VIPR2, and ZSCAN23 were consistently downregulated in nine cancers." (PMID 28060724, 2017). "Similarly, low expressions of CYTH3, NOVA1, and EPHA6 were highly correlated with longer OS in patients with other types of cancers." (PMID 36506313, 2022). "Together, NOVA1 and PTBP1 have a role in driving the FL splicing of hTERT in cancer." (PMID 30568224, 2019). "Interestingly, intratumoral (but not peritumoral) Nova1, correlated to poor survival rate and increased occurrence of cancer relapse." (PMID 24608171, 2014).
tumor (24 papers, 2014 to 2025). "Noteworthy, MBNL1 was highly expressed in both tumor and stroma cells, while NOVA1 and RBMS3 were dominantly expressed in tumor stroma." (PMID 39980011, 2025). "Regardless of luminal subtype (A/B), LM cells had increased expression of ELOVL5, EFHD1, NEK10, LYPD6 and NOVA1, among others, relative to the tumor cells." (PMID 39478117, 2024). "The expression of neuro-oncological ventral antigen 1 (NOVA1) was suppressed in GC, and ectopic NOVA1 expression in tumor cells contributes to tumor growth and a poor prognosis." (PMID 38361095, 2024). "To this end, since their expression was augmented in tumor tissue, we performed silencing experiments of NOVA1, PRPF8 and SRSF10 in UMC-11 and NCI-H727 cells, two distinct broadly used pulmonary carcinoid cell models." (PMID 38049848, 2023). "It has been reported that WWC2 gene can inhibit tumor metastasis, while NOVA1 usually plays an oncogenic role." (PMID 35799607, 2022). "MALAT1 upregulation correlates with tumor cell proliferation, invasion and chemoresistance through Nova1 regulation." (PMID 34425750, 2021). "NOVA1 is a neuron-specific pre-mRNA binding splicing factor, which is highly expressed in tumor cells." (PMID 32589614, 2020). "The aberrant expression of Nova1 in tumor cells interferes the RNA-binding activity and triggers host immune response, leading to the development of POMA." (PMID 24608171, 2014). "The difference of the percentage of Nova1 positive cell in the tumor and peritumoral tissues was borderline statistical significant." (PMID 24608171, 2014). "In the present study, we found that Nova1 is expressed in cytoplasm of both tumor and peritumoral tissues of HCC patients." (PMID 24608171, 2014). "The tumor-suppressive effect was mediated via the repression of NOVA1 (neuro-oncological ventral antigen 1)." (PMID 25299073, 2014). "In this study, Nova1 was identified in both tumor and paired peritumoral tissues of 91 HCC patients." (PMID 24608171, 2014). "The mutation frequencies of FAM83B, ZNF585A, DMBT1, ACACA, NOVA1, PCTH1, and ADAMTS7 were significantly higher in the high‐risk group, suggesting that these mutations may contribute to tumor development." (PMID 35616307, 2023). "In this study we first conducted a tumorigenticity test in nude mice and found that Nova1 could improve tumor growth in vivo." (PMID 27733149, 2016). "In this study, we found that overexpressed intratumoral Nova1 was associated with poor survival rate and increased recurrence rate of HCC, especially early recurrence, and was an independent prognostic factor for overall survival rate and tumor recurrence." (PMID 24608171, 2014). "Nova1 was presented both in tumor and peritumoral tissues, but much higher in tumor tissues." (PMID 24608171, 2014). "Nova1 was focally expressed in cytoplasm of both peritumoral and tumor cells." (PMID 24608171, 2014). "Of the 11 neoplasm-related genes in these subclusters, the expression of six (ANGPT2, TP73, NOVA1, CDH11, CXCL12, and LAMA1) were significantly repressed in KRT and one (EPHA2) was higher expressed in KRT compared with IMU." (PMID 37654626, 2023). "Specifically, the splicing machinery components KHDRBS1, NOVA1, PRPF8, SNW1, SRSF1, SRSF10 and SRSF9 were overexpressed in tumor tissue." (PMID 38049848, 2023). "The results indicated that the expression levels of these four SFs, including NOVA1, RBM4, HNRNPC, and HNRPLL, in tumor tissues were significantly decreased, compared to those in normal tissues." (PMID 35832652, 2022). "We also compared the expression level of these SFs in GBM tumor tissues and adjacent normal tissues and found that 7 factors were significantly dysregulated, including HNRNPA1, HNRNPC, HNRPLL, NOVA1, SF3B1, KHDRBS2, and TIA1." (PMID 34326872, 2021). "Neuro‐oncological ventral antigen 1 (NOVA1) is a novel RBP and plays an important role in tumour development." (PMID 29498217, 2018).
tumor (continued). "Moreover, NOVA1 and ESRP2 expression were statistically increased in OSCC with an expansive front of tumor invasion compared to OSCC with an infiltrative front of tumor invasion (p = 0.04 and 0.06, respectively)." (PMID 39000035, 2024). "Interestingly, 16 of the 34 components examined (47.1%) were altered and, in line with our Discovery cohort, KHDRBS1, NOVA1, PRPF8, SNW1, SRSF1, and SRSF9 were also overexpressed in tumor tissue in this external cohort." (PMID 38049848, 2023). "Therefore, these target genes can also provide new directions for future tumor treatment, especially the five genes DLC1, LRFN5, NOVA1, POU3F2 and PRICKLE2 which were positively related to the overall survival time." (PMID 35578189, 2022). "SNAI1/SLUG expression (another marker of EMT) in tumor cells was related to NOVA1 expression status in T lymphocytes and stromal spindle cells/fibroblasts, but not to NOVA1 status in tumor cells." (PMID 31375778, 2019). "Taken together, all these data support the hypothesis that Nova1 plays a role in HCC developments and may serve as a prognostic marker for tumor relapse and progression." (PMID 24608171, 2014).
neurological diseases (2 papers, 2021 to 2023). "NOVA1 is a master regulator of alternative splicing in the central nervous system with potential links to neurological diseases." (PMID 37470786, 2023).
NOVA1 also shares sentences with these, for which no sentence is quoted: colorectal cancer (2 papers); depression (2); oligodendroglioma (2); Opsoclonus (2); osteosarcoma (2); thyroid cancer (2); acute myeloid leukemia (1); amyotrophic lateral sclerosis (1); B cell lymphoma (1); cerebellar degeneration (1); cutaneous nevus (1); Impaired glucose tolerance (1); Laryngospasm (1); neurodegenerative disease (1); Obesity (1); ovarian carcinoma (1); pancreatic cancer (1); prostate carcinoma (1); psoriasis (1); sporadic amyotrophic lateral sclerosis (1); squamous cell carcinoma (1).